CD4 (CD4 molecule)
Diseases named in the same sentence as CD4 in open-access papers (continued):
Sharing a sentence is not in itself a finding about the gene and the disease.
lung cancer (continued). "Other classical hallmarks of immunosenescence have also been examined, with reports of low CD19+ B cell numbers in patients with lung cancer, along with a decreased ratio of CD4+ T cells to CD8+ T cells, which has also been shown in patients with late-stage melanoma." (PMID 28751932, 2017). "Interestingly, earlier studies described a correlation between the presence of CD4+ T cells in the bronchoalveolar lavage of irradiated breast or lung cancer patients and the development of pneumonitis." (PMID 28018357, 2016). "In lung cancer rice model, cyclophosphamide could inhibit lung metastasis, reduce tumor weight and volume, and decrease the CD4+CD25+ T cells in spleen and metastasis foci." (PMID 26462021, 2015). "However, more recently lung cancer studies have shown that CD27 expression on human CD4+CD25+ Tregs positively correlates with their suppressive activity in vitro and the expression of FOXP3." (PMID 25951351, 2015). "In our research, the hypermethylation status in CD4+ T cells in lung cancer patients suggests that the presence of cancerous cells may contribute to an altered expression profile." (PMID 24244422, 2013). "The depletion of CD4+ T cells one day before vaccination with SA-4-1BBL admixed with survivin (SVN) as self TAA had no detectable effect on the therapeutic efficacy of the vaccine in the 3LL lung carcinoma model expressing SVN." (PMID 24066030, 2013). "Thus, TIM-3+CD4+ T cells were predominantly Tregs and most of Tregs within lung cancer TILs highly up-regulated TIM-3 expression." (PMID 22363469, 2012). "Besides CD8+ TILs, TIM-3 was found expressed on CD4+ TILs in human lung cancer as well as in the mouse transplanted tumor." (PMID 22363469, 2012). "Even though the role of infiltrating CD4+ T-cells as an independent factor predicting favorable outcome is still controversial, these studies suggest that low infiltration of CD8+ T-cells is associated with a poor clinical outcome in lung cancer patients." (PMID 23118782, 2012). "Accordingly, increased SPTBN1 expression (and over-representation of aTOH1/cTOH3 in controls over cases) could plausibly protect against lung cancer by increasing immune surveillance, given that we know that smoking suppresses the CD4/CD8 T cell ratio." (PMID 22384118, 2012). "The GSVA assay revealed that the top 100 gene set highly expressed in GZMA CD4 T cells was associated with better overall survival in LUAD patients, suggesting that the presence of GZMA CD4 T cells may provide potential benefits for lung cancer patients (sTable 2)." (PMID 40959273, 2025). "However, another study showed the opposite result when analyzing patients with lung cancer, which may be explained by the heterogeneous function of HLA DR+ CD4+ T cells in different cancers." (PMID 40564200, 2025). "In the not so distant far, assays of CD4 T-cells derived from mediastinal lymph nodes might identify patients with IPF at greater risk for progression or lung cancer development and patients more likely to experience benefit from targeted immunotherapy." (PMID 37964265, 2023). "Furthermore, DSCC1 expression correlated negatively with immune infiltration levels of multiple immune cell types in lung cancer and the proportions of B cells, CD4 + T cells, CD8 + T cells, and DC cells were lower in the high DSCC1 expression group than in the low DSCC1 expression group." (PMID 37742009, 2023). "However, the oxidative stress response caused by the increased ROS produced by MDSCs can produce related free radicals and immunomodulatory cytokines, which can inhibit host CD8+ and CD4+ T-cell responses, thus promoting the metastasis and the progression of lung cancer." (PMID 37857728, 2023). "In this part, we further investigated whether WDR6 expression was associated with immune cell infiltration in lung cancer patients, finding that the expression of WDR6 obviously related to CD8+ T cell and CD4+ T cell in LUAD, while only correlated with CD4+ T cell in LUSC." (PMID 36039642, 2022).
lung cancer (continued). "Furthermore, as HIV infection directly compromises the T cell compartment by infecting and killing CD4+ T cells, the increased incidence of other cancers (Hodgkin’s lymphoma, anal cancer, lung cancer) was found to inversely correlate with the declining CD4+ T cell counts." (PMID 36497356, 2022). "Furthermore, ex vivo treatment of tumor-infiltrating CD4+ T cells with activin-A bestowed them with robust effector properties which were maintained upon therapeutic transfer in vivo and empowered them to protect against lung cancer progression." (PMID 34548096, 2021). "Immune cell malfunction of patients with lung cancer may reduce the CD3+ to CD4+ ratio." (PMID 33936245, 2021). "Moreover, SDCBP may increase the immune infiltration of B cells, CD8+ T cells, CD4+ T cells, macrophages, neutrophils and dendritic cells in different lung carcinoma." (PMID 34137173, 2021). "Importantly, the role of systemic CD4 T cells has been emphasized in two recent studies conducted in lung cancer where the presence of functional CD4 Th1 cells in blood at the baseline (pre-existing immunity) proved to predict clinical response to anti-PD-1/PD-L1 immunotherapy." (PMID 32630460, 2020). "Interestingly, in addition to being more frequent, lung cancer patient PTCAs showed a higher MFI of CD42b (both CD4+ and CD8+) than those from healthy volunteers which may suggest more platelets per T cell." (PMID 32776968, 2020). "However, less studies focussed on Notch receptors expression in CD4+ T cells in lung cancer." (PMID 30473538, 2018). "As we observed a high proliferation of CD4+ T cells induced by DC-based lung cancer vaccine, it is tempting to speculate that CD4+ T cells might play an important role in shaping anti-cancer responses after DC-based HHP lung cancer immunotherapy in NSCLC patients." (PMID 28187172, 2017). "Furthermore, the balance of these CD4+ T cell populations at local and systemic sites may be clinically relevant in evaluating lung cancer prognosis." (PMID 27784305, 2016). "Although both Treg and Th17 cells exert a diverse set of cancer-related functions, these CD4+ T cell subsets may have opposing prognostic values in lung cancer, with a higher ratio of Tregs to Th17s correlating with more aggressive and advanced-staged malignancies." (PMID 27784305, 2016). "Indeed, identification of an immunogenic epitope of EZH2 recognized by CD4 T-cell in lung cancer, could serve as a potent immunogenic target inducing both CD4 and CD8 T-cell anti-tumor responses." (PMID 27793053, 2016). "Here, we found that Loxoribin, one of the TLR7 ligands, could inhibit tumor growth in xenograft models of colon cancer and lung cancer, and these anti-tumor effects of Loxoribin were mediated by promoting CD4+T cell proliferation and reversing Treg-mediated suppression via dendritic cells (DCs)." (PMID 25593198, 2015). "In this study, we found that Loxoribin, one of the TLR7 ligands, could inhibit tumor growth in vivo in both colon cancer and lung cancer xenograft models, and these antitumor effects of Loxoribin were mediated by promoting CD4+T cell proliferation and reversing Treg-mediated suppression via DCs." (PMID 25593198, 2015). "For example, although the numbers vary somewhat, in lung cancer, it has been reported that between 30%–60% of CD8 TILs and 5%–40% of CD4 TILs express CD69 and/or CD103 and were categorized as TRM." (PMID 40285480, 2025). "In non‐small cell lung cancer patients, levels of T lymphocytes, natural killer cells, CD8+ T cells, and CD4+ T cells are diminished compared with those in healthy individuals." (PMID 39749673, 2025). "In one study, the levels of CD3+, CD4+, CD4+/CD8+, and CD19+ cells in the peripheral blood of lung cancer patients before radiotherapy were significantly lower than those in healthy controls (p < 0.05), which is consistent with our findings." (PMID 41584574, 2025).
lung cancer (continued). "Anxiety and depression impair immune function in lung cancer patients, while olanzapine enhances CD3, CD4, and NK cell activity and reduces psychological distress, suggesting its potential as an adjunct in cancer immunotherapy." (PMID 41446305, 2025). "Lung cancer patients with concurrent anxiety and depression exhibited elevated CD3, CD4, CD8, NK cell counts, and CD4/CD8 ratio, alongside reduced Neutrophil-to-Lymphocyte Ratio (NLR) (P = 0.044, 0.001, 0.022, 0.039, 0.007, 0.003)." (PMID 41446305, 2025). "In lung cancer, T lymphocytes dominate the tumor microenvironment (TME), where CD4+ T cells coordinate immune responses via cytokine secretion, while CD8+ cytotoxic T lymphocytes (CTLs) eliminate neoplastic cells expressing tumor neoantigens." (PMID 41394845, 2025). "Consistent with previous studies, we observed that lung cancer MPE contained large numbers of CD3+ T cells, skewed largely towards CD4+ T cells." (PMID 40285480, 2025). "In the context of lung cancer, TIM-3 exhibits a high frequency of expression on both CD4(+) and CD8(+) TILs." (PMID 40724985, 2025). "Under tumor microenvironment in lung carcinoma condition, DCs are instructed to secrete TGF‐β, followed by promoting the acquisition of Treg phenotype by CD4+ T cells." (PMID 39083441, 2025). "The authors pinpointed intratumoral CD68-positive macrophages, M1 macrophages and intrastromal CD4+ cells, CD4+ FOXP3- cells, CD8+ cells and PD-L1+ cells to be the most robust prognostic biomarkers for DFS in lung cancer." (PMID 38674427, 2024). "It has been proved that CD3 + T lymphocytes, CD4 + T lymphocytes and the rate of CD4/CD8 are closely correlated with the prognosis of lung cancer." (PMID 38303053, 2024). "Further observation of the infiltration patterns of CD4 + and CD8 + T cells revealed a consistent trend in COPD and lung cancer." (PMID 38605291, 2024). "We also found that in lung cancer patients receiving neoadjuvant immunotherapy, more infiltrated CD3+, CD4+, CD8+, or CD68+ cells were detected in pre-treatment tumor tissues from patients achieving pathologic complete response (pCR)." (PMID 38762546, 2024). "The deletion of HDAC2 induced the transition from M2 to M1‐like TAM, activated T‐cell activation‐related signaling pathways, reduced CD4+ T cells and increased CD8+ T‐cell infiltration, and inhibited the lung cancer progression." (PMID 38783893, 2024). "The result of xCell suggested that scores of several types of T cells, including CD4+ T cells and CD8+ T cells, were significantly lower in BrM tumors when compared to primary lung cancer lesions." (PMID 39593114, 2024). "(a) Prediction strategy to classify CD4+, CD8+ T, and natural killer (NK) cells by applying antibody-derived tag (ADT) data from lung cancer." (PMID 39514276, 2024). "It correlated with CD4 + T cell count and CD4+/CD8 + T cell ratio, as well as with the pathological type, distant metastasis, and clinical stage of HIV-related lung cancer, all with statistical significance (P < 0.05)." (PMID 39080685, 2024). "The proportion of CTLA-4+ cells in CD4+ T cells and CD8+ T cells has been found significantly higher in MPE than peripheral blood in lung cancer patients." (PMID 38475858, 2024). "CTSG protein correlates with CD4 + T cell count, CD4 + T/CD8 + T cells, pathological type, distant metastasis and clinical stage in HIV-related lung cancer." (PMID 39080685, 2024). "TIGIT was highly expressed on CD4+ T cells and CD8+ T cells in all three tumors, moderately expressed on NK cells in colorectal cancer, and moderately expressed in monocytes in lung cancer." (PMID 39120585, 2024). "According to another report, CD4+ Th9 and CD4+ Th17, through secretion of IL-9 and IL-17, respectively, induced EMT in lung cancer cells." (PMID 39201656, 2024). "The metabolism of CD4+ and CD8+ memory T cells in lung cancer patients contributes to long-term immunity." (PMID 37857728, 2023).
lung cancer (continued). "Research has shown that the fraction of CD4 + CD25 + Foxp3 + Tregs in the TME and functional modifications of T lymphocyte subsets are essential for the immune evasion of lung cancer cells." (PMID 37641132, 2023). "The available data suggests lung cancer cell-derived exosomes affect DCs leading to an increase in the development of Treg cells in the TME, a reduction in the quantity of CD4 + T cells and inhibition of IFN-γ generation." (PMID 37641132, 2023). "We analyzed PD-1, PD-L1 expression and CD4/CD8 ratio in mediastinal lymph nodes of thirty-three patients (n = 33) (IPF: 14, IPF and lung cancer: 9, lung cancer: 10)." (PMID 37964265, 2023). "In patients with lung cancer, TIM-3 is characterized by a relatively high positive expression rate on both CD4( +) and CD8( +) TILs from human lung cancer tissues." (PMID 37567938, 2023). "CD4+ T cells with CD62LlowCCR4-CCR6+ phenotype are correlated with the progression-free survival and overall survival of lung cancer patients after PD-1 blockade therapy." (PMID 38062068, 2023). "Specifically, we found that CXCR3 decreased in the CD4+ T and CD8+ T cells in patients with lung cancer." (PMID 36688994, 2023). "Evidence of safety and efficacy in Kaposi sarcoma, NHL, lung cancer, and liver cancer were found in a prospective phase 1 study of pembrolizumab in PLWH with a CD4 count > 100 cells/μL and advanced malignancy." (PMID 37799470, 2023). "Putatively terminally-differentiated CD4 + EMRA and CD8 + EMRA T cells decreased after BT treatment, whereas CD4 + naïve T cells increased also in patients with advanced lung cancer, immediately after platinum-based chemotherapy." (PMID 37291596, 2023). "In this study, we aimed to compare the functionality of CD4+, CD8+, NK+, NKCD4+ and NKCD8+ T cell in the PBMCs of lung cancer patients before, during, and after induction of chemotherapy by analyzing their expressions of GzB." (PMID 37580655, 2023). "Several studies have also demonstrated that lung cancer patients have lower levels of CD4+/CD8+ ratio, CD4+T cells, NK cell levels, and higher regulatory T cells (Tregs) than healthy subjects." (PMID 37701442, 2023). "After culture, the expression of GzB by cytotoxic CD8+ T, CD4+ helper T cells, NK, CD4+ NK T and CD8+ NK T cells were found to decrease significantly in lung cancer patients before and during induction of chemotherapy." (PMID 37580655, 2023). "We performed authentication testing of the correlation between LRRC3B expression and infiltration of CD4+/CD8+ T cell, using multiplexed fluorescence immunohistochemistry (mIHC), in the lung cancer tissue array." (PMID 36798137, 2023). "This differential in TIGIT expression between Tregs and CD4 and CD8 T cells is also maintained in the tumor microenvironment, demonstrated by higher levels of 5 different lung cancer dissociated tumor cultures (DTC), vs normal peripheral cells." (PMID 38022590, 2023). "HSPA1A is upregulated in CD4+ and CD8+ T cells after treatment with immune checkpoint blockers in various cancers, such as renal cancer, lung cancer, and basal cell carcinoma." (PMID 37762493, 2023). "First, we characterized the absolute number of WBC and lymphocytes and the relative frequencies of the CD3+, CD4+, and CD8+ T cells and NK cells in both lung cancer patients and healthy individuals." (PMID 36901716, 2023). "We found that in lung cancer, ABI3BP was significantly positively correlated with B memory cells, CD4+ T memory cell rest, Tregs, B cell, T cell, CD4+ T, myeloid dendritic cell activation, and endothelial cells." (PMID 36744181, 2022). "In our experimental setting, we showed inhibition of both CD4 and CD8 T cell proliferation, by lung cancer derived EVs from LT73." (PMID 36203609, 2022). "Here, we confirmed that the overexpression of POSTN was correlated with several immune cell infiltration in lung cancer tissues, including B cells, CD8+ T cells, CD4+T cells, macrophages, neutrophils, and dendritic cells." (PMID 35508298, 2022).
lung cancer (continued). "For example, previous studies have shown that the abundance of CD4+, CD8+ T cells, and neutrophils are prognostic factors in lung cancer." (PMID 35938038, 2022). "In another patient with leptomeningeal metastasis of lung cancer, the ZC3H12D expression was relatively higher in CD8 T cells and CD4 T cells." (PMID 35090416, 2022). "On the other hand, CCR6+ILC3s (Lti cells) have an anti-tumoral role in chemotherapy treated lung cancer by secreting CXCL10, which is a chemoattractant of CD4+ and CD8+ T cells." (PMID 36341381, 2022). "CD8+ T cells producing CXCL13 were reported in lung cancer and ovarian cancer, whereas an analysis in nasopharyngeal cancer reported that most subsets of T cells producing CXCL13 were CD4+ T cells." (PMID 35552285, 2022). "We firstly evaluated all the 303 lung cancer patients in this study, the results showed that CD3, CD4, CD8, and CD16 + 56+ T cells were significantly decreased in the ATB group (n = 145) than that in the non-ATB group (n = 158) (p < 0.01)." (PMID 36384523, 2022). "The expression of BTLA was increased in the CD4+ and CD8+ T cells of pleural fluid of patients with lung cancer." (PMID 34163466, 2021). "Another meta-analysis clarified that high level of CD3+, CD4+, and CD8+ T cells infiltration showed better OS in lung cancer patients." (PMID 33859531, 2021). "MPE-derived CD4+ and CD8+ T cells in mesothelioma and lung cancer exhibit a memory phenotype prior to treatment." (PMID 33987104, 2021). "Because we observed an increase in functional anti-tumor CD8 T cells (increased ratio of CD8: CD4, CD25) we interrogated if the combination of MSU42011 with anti-PD1 or anti-PDL1 antibodies would be beneficial in the A/J lung cancer model." (PMID 34638488, 2021). "We found that MTR OralGem administration enhanced PD-1 expression in lung tumor-infiltrating CD4+ and CD8+ T effectors and boosted PD-L1 levels in DC and tumor cells, sensitizing the TME to anti-PD-1 immunotherapy in the syngeneic lung cancer model." (PMID 33920884, 2021). "Lung cancer patients with longer overall survival had enhanced numbers of CD3, CD4, and CD8 T cell in the blood at baseline, and high lymphocyte counts were associated with better overall survival in recurrent NSCLC patients." (PMID 35008239, 2021). "The expression of inhibitory receptors on CD4+ and CD8+ T cells in MPE have been reported in multiple studies for mesothelioma and lung cancer." (PMID 33987104, 2021). "Further, another study showed that circulating T cells (CD4+T and CD8+T cell) express upregulated levels of PD‐1, which correlated with a poorer clinical outcome in patients with lung cancer." (PMID 34143443, 2021). "In non–small-cell lung cancer, higher peripheral proliferating CD8+ T cells and lower CD4+ T cells, compared with healthy controls, have been observed." (PMID 33777727, 2021). "Based on MIXTURE deconvolution of the RNAseq datasets, lung cancers demonstrated significantly higher levels of immune cells, including CD8+ T cells, CD4+ T cells, Tregs, dendritic cells, and macrophages." (PMID 33985562, 2021). "Lung cancer cell-derived exosomes act on DCs, thereby increasing Treg differentiation in the TME, decreasing the proportion of CD4+ T cells, and decreasing IFN-γ production." (PMID 34193120, 2021). "A previous study shows that activated memory CD4 T cells and helper T cells are positively correlated with improvement in survival AMONG lung cancer patients." (PMID 34855841, 2021). "The proportion of CD4+CD25+Foxp3+ T regulatory cells (Tregs) and functional alterations of T lymphocyte subsets in the TME are critical for the immune escape of lung cancer cells." (PMID 34193120, 2021). "Inhibitory receptors TIM-3, LAG-3, CTLA-4 and PD-L1 are also expressed on MPE CD4+ and CD8+ T cells at greater proportions than matched peripheral blood samples in mesothelioma and lung cancer patients." (PMID 33987104, 2021).